TET2 (tet methylcytosine dioxygenase 2)
Diseases named in the same sentence as TET2 in open-access papers (continued):
Sharing a sentence is not in itself a finding about the gene and the disease.
MALT lymphoma (2 papers, 2021). An indolent, extranodal type of non-Hodgkin lymphoma composed of small B-lymphocytes (centrocyte-like cells). "Inactivation of chromatin remodeling genes are frequently observed in MALT lymphomas, with the most common mutated genes being TET2, KMT2D, CREBBP, TBL1X1, KMT2C, MT2C, EP300, among others." (PMID 35008340, 2021). "The finding of remarkably variable involvement of TET2 mutations in MALT lymphoma of different sites (86% in thyroid, but <8% in other sites) is intriguing as the mutation commonly occurs in haematopoietic stem/progenitor cells in individuals with clonal haematopoiesis of indeterminate potential." (PMID 34021249, 2021). "As TET2, a methylcytosine dioxygenase, may influence DNA mutagenicity, and Tet deficient germinal centre B-cells showed hypersomatic mutations skewing towards transition changes, we compared mutation burden and spectrum according to the TET2 mutation status in thyroid MALT lymphoma." (PMID 34021249, 2021). "Several chromatin remodeling and transcriptional regulators are recurrently mutated in MALT lymphoma of different sites, including TBL1XR1, TET2, MLL2/KMT2D and CREBBP." (PMID 35008340, 2021). "Among MALT lymphoma of various sites, the most prominent findings were frequent CD274 (52.6%), TNFRSF14 (52.6%), TET2 (85.5%) and TNFAIP3 (30%) mutations in the thyroid cases." (PMID 34021249, 2021).
mast cell leukaemia (2 papers, 2014 to 2018). "To model the cooperation between loss of function of TET2 and the KIT D816V mutation in vitro, we knocked down (KD) TET2 in a human mast cell leukemia cell line (HMC-1.2) harboring the KIT D816V mutation." (PMID 24788138, 2014).
metastatic disease (2 papers, 2025). "Loss of TET2 is a potentially informative biomarker of PCa progression, where the acquisition of somatic TET2 mutations is associated with an increased risk of metastatic disease." (PMID 40116537, 2025). "Although TET2 mutation is primarily associated with early‐stage cancer development, there are reports of TET2 mutation specific to metastatic disease in some solid tumors." (PMID 40116537, 2025). "Previous clinical studies also proved that reduced TET2 expression is correlated with advanced Gleason scores, metastatic disease, and poor prognosis and serves as an independent prognostic marker in PCa." (PMID 40297177, 2025).
metastatic melanoma (2 papers, 2017 to 2018). A melanoma that has spread from its primary site to another anatomic site. "In human metastatic melanoma cells, deficiency of HIF-1α increased TET2 mRNA and protein expression, and ascorbic acid induced TET2 dependent 5 hmC formation." (PMID 29666467, 2018). "Treatment of the metastatic melanoma cell line SK-MEL-1, which expressed very low levels of TET2 and TET3, with LY9702161, elevated their expression levels." (PMID 27852070, 2017).
multiple sclerosis (2 papers, 2015 to 2024). A progressive autoimmune disorder affecting the central nervous system resulting in demyelination. "The biological effects of TET2 hypermethylation, as reflected by lower 5-hmC levels, had been observed in multiple sclerosis." (PMID 25557833, 2015).
myelodysplastic/myeloproliferative neoplasm (2 papers, 2020 to 2023). A category of clonal hematopoietic disorders that have both myelodysplastic and myeloproliferative features at the time of initial presentation. "For TET2 and SRSFP95H mutations, myeloid bias was associated with CHIP or the initiation of myelodysplastic/myeloproliferative syndrome, whereas for DNMT3A multipotent stem cell origin was described in the context of CHIP." (PMID 32526214, 2020).
neutropenia (2 papers, 2021 to 2022). A decrease in the number of neutrophils found in the blood. "Finally, 68% of the tested cases displayed at least one somatic mutation, most commonly SF3B1, TET2, ASXL1, and SRSF2, associated with older age, presence of neutropenia, and lower response to ESAs." (PMID 35392224, 2022).
non-alcoholic fatty liver disease (2 papers, 2022 to 2023). "The TET2 p.Ile1762Val variant has also previously been reported to correlate with liver PPARƴ coactivator 1 alpha (PGC1A)-methylation levels and non-alcoholic fatty liver disease." (PMID 36009574, 2022).
Osteopenia (2 papers, 2018 to 2019). Osteopenia is a term to define bone density that is not normal but also not as low as osteoporosis. "Here we show that depletion of Tet1 and Tet2 results in impaired self-renewal and differentiation of bone marrow MSCs (BMMSCs) and a significant osteopenia phenotype." (PMID 29858571, 2018). "The depletion of Tet1 and Tet2 may lead to hypermethylation of the P2rX7 promoter to block miR-297a-5p, miR-297b-5p, and miR-297C-5p release, leading to downregulation of Runx2 signaling and osteopenia phenotype." (PMID 29858571, 2018). "In conclusion, depletion of Tet1 and Tet2 results in BMMSC impairment and an osteopenia phenotype." (PMID 29858571, 2018).
peritonitis (2 papers, 2021 to 2025). Inflammation of the peritoneum (tissue that lines the abdominal wall and covers most of the organs in the abdomen). "Second, macrophage TET2 expression is essential for antibacterial responses, protecting against conditions like peritonitis and abdominal sepsis, partly by inhibiting proinflammatory cytokines such as IL-6." (PMID 40794443, 2025). "Moreover, we demonstrate a role for macrophage Tet2 in limiting the growth of E. coli in vitro, which was associated with increased growth and dissemination of E. coli in mice with myeloid cell-specific Tet2 deficiency in a model of peritonitis and abdominal sepsis." (PMID 35011643, 2021). "Collectively, these data suggest that Tet2 is involved in antibacterial defense mediated by PMs during E. coli induced peritonitis." (PMID 35011643, 2021). "In mice, in vivo, the inhibitory effect of Tet2 on inflammatory activation of macrophages in atherosclerosis, colitis and peritonitis was regulated through histone deacetylases (HDACs)." (PMID 35011643, 2021). "We here sought to determine the expression and function of Tet2 in macrophages upon exposure to lipopolysaccharide (LPS), and in the host response to LPS induced lung and peritoneal inflammation, and during Escherichia (E.)coli induced peritonitis." (PMID 35011643, 2021). "Collectively, these data suggest that Tet2 represses cytokine gene expression in PMs exposed to LPS as well as peritoneal cytokine release during LPS-induced peritonitis without affecting cell influx into the peritoneal cavity." (PMID 35011643, 2021).
preeclampsia (2 papers, 2021 to 2024). Preeclampsia is a hypertensive disorder of pregnancy that is characterized by new-onset hypertension with proteinuria presenting after 20 weeks of gestation, and depending on mild or severe forms may initially present with severe headache, visual disturbances, and hyperreflexia. "In human, downregulation of TET2 expression was detected in placenta from the preeclampsia patients and was related to the reduced trophoblast migration and invasion abilities." (PMID 38886218, 2024). "In preeclampsia, almost 90% of vessels stain for TET2 with neutrophils infiltrated into the vessel wall, as compared to only 16% of vessels in normal pregnancy with staining." (PMID 34209594, 2021). "This close relationship between PAR-1 and TET2 likely has important implications for vascular inflammation in preeclampsia." (PMID 34209594, 2021). "Nuclear staining suggests TET2 is active in preeclampsia, and activation involves translocation from the cytosol to the nucleus just as observed for TET2 translocation induced by protease activation of PAR-1." (PMID 34209594, 2021). "Expression and activation of neutrophil TET2 are increased in preeclampsia." (PMID 34209594, 2021).
prostate tumor (2 papers, 2017 to 2019). "Here, we describe seven promising targets of epigenetic modification directed by TET2 loss by analyzing their methylation and expression profiles in both prostate-derived cell lines and prostate tumors from the Cancer Genome Atlas (TCGA)." (PMID 30917865, 2019). "Promoter methylation gain of one such promising candidate gene, ankyrin repeat and SOCS-box containing protein 2 (ASB2), within the TET2-target site is investigated in an independent series of primary prostate tumors." (PMID 30917865, 2019). "Next, we assessed the ability of these 60 TET2-target genes to distinguish between prostate tumor and normal samples (n = 35) expressing variable levels of TET2, in either all tumors with expression data available (n = 423) or in matched tumor and normal pairs only (n = 35)." (PMID 30917865, 2019). "Furthermore, methylation array probes in the TCGA dataset, which were proximal to the highly conserved, differentially methylated sites identified in our TET2-knockout cells, were able to significantly distinguish between matched prostate tumor and normal prostate tissues (n = 50 pairs)." (PMID 30917865, 2019).
renal fibrosis (2 papers, 2023). A final common manifestation of a wide variety of chronic kidney diseases characterized by glomerulosclerosis and tubulointerstitial fibrosis. "In the mouse models described by Jaiswal and Sano, the presence of variations in TET2 and DNMT3a was associated with greater glomerulosclerosis and greater renal fibrosis after exposure to angiotensin II." (PMID 37763205, 2023).
sarcoma (2 papers, 2022). A usually aggressive malignant neoplasm of the soft tissue or bone. "Based on the analysis of m5C regulator mutations in the TCGA cohort of sarcomas, we found that TET2 had the highest mutation rate." (PMID 36684288, 2022).
scurvy (2 papers, 2021 to 2022). A condition that develops in people who do not consume an adequate amount of vitamin C in their diet. "In this way, vitamin C deficiency, in combination with other mutations, such as those that inactivate Tet2, can favor the development of myeloproliferative pathologies." (PMID 33535710, 2021). "Transplant of mutant cells into Gulo−/− mice increased proliferation of myeloid lineage cells in relation to control animals, thus indicating that vitamin C deficiency cooperates with this mutation to promote myelopoiesis, a process that would be mediated mainly by TET2." (PMID 33535710, 2021). "Importantly, deletion of 5hmC-writers, Tet1 and Tet2, in Vitamin C-sufficient murine bone causes severe skeletal defects which mimic bone phenotypes of Vitamin C-insufficient Gulo knockout mice, a model of Vitamin C deficiency and scurvy." (PMID 36202795, 2022).
thyroid (2 papers, 2021 to 2022). "Two thyroid MZL (TMZL) studies showed a high prevalence of TET2 mutations (61%, 11/18), which statistically significantly exceeded that in salivary gland MZL (SAMZL), gastric MZL (GMZL), pulmonary MZL (PMZL), and ocular adnexal MZL (OMZL)." (PMID 34494161, 2022).
thyroid lymphoma (2 papers, 2021 to 2025). A lymphoma primarily involving the thyroid gland. "It remains to be investigated how TET2 inactivation by mutation may reshape peripheral tolerance and impact the acquisition and selection of cooperative oncogenic changes in the genesis of thyroid lymphoma." (PMID 39722652, 2025).
varicocele (2 papers, 2024). A condition characterized by the dilated tortuous veins of the spermatic cord with a marked left-sided predominance. "A study showed that another possible mechanism of the observed hypomethylation could be the overexpression of the ten-eleven translocation 2 (TET2) protein in the rodent varicocele model, which, in turn, has demethylase activity." (PMID 39063558, 2024). "In a varicocele-induced rat model there was an increased expression of TET2 mRNA, a key regulatory protein in the demethylation pathway, and this overexpression may have contributed to the global hypomethylation observed in rats with varicoceles." (PMID 38392299, 2024).
allergic asthma (1 paper, 2025). A asthma with a basis in a pathological type I hypersensitivity reaction. "For instance, GATA2, TET2, and TWIST1 are enriched for more than one gene co-occurrence pair and are known to influence allergic asthma (63, –65)." (PMID 40504147, 2025).
amyloid (1 paper, 2021). "In middle-aged 2 × Tg-AD mice, over-expression of Tet2 in the dentate gyrus (DG) improves memory impairment and reduces amyloid burden, suggesting a neuroprotective role of Tet2 in neuronal survival." (PMID 34389067, 2021).
aneurysm (1 paper, 2026). Bulging or ballooning in an area of an artery secondary to arterial wall weakening. "Thus, we modeled clonal hematopoiesis by competitively transplanting ten-eleven translocation 2-deficient (Tet2-deficient) bone marrow into apoliprotein E-KO (Apoe-KO) mice and induced aneurysms with angiotensin II." (PMID 41739588, 2026).
aortic aneurysm (1 paper, 2026). A ruptured aneurysm located in the wall of the proximal portion of the descending aorta proceeding from the arch of the aorta. "Thus, Tet2-driven clonal hematopoiesis accelerated aortic aneurysm progression through MMP9-producing, osteoclast-like macrophages and therefore represents a tractable therapeutic axis." (PMID 41739588, 2026).
Atherosclerotic lesion (1 paper, 2016). A lesion associated with atherosclerosis, a multifactorial and multipart progressive disease manifested by the focal development within the arterial wall of lesions, that ranges from the development of a fatty streak, plaque progression, and plaque disruption. "In the present study, the expression levels of TET2 and 5hmC obviously decreased in atherosclerotic lesions." (PMID 27821816, 2016).
autoimmune pancreatitis (1 paper, 2021). "The expression of TET2 in β cells in autoimmune pancreatitis and T1D onset plus some autoantibody + individuals was significantly higher compared to conditions without inflammation." (PMID 34417463, 2021).
B-cell acute lymphoblastic leukemia (1 paper, 2017). A neoplasm of lymphoblasts committed to the B-cell lineage, typically composed of small to medium-sized blast cells. "In humans, TET1 and TET2 have been previously shown to be concomitantly downregulated in B cell acute lymphoblastic leukemia and to have overlapping functions in B cell development and leukemogenesis." (PMID 29029465, 2017).
B-cell neoplasm (1 paper, 2016). A group of heterogeneous lymphoid tumors generally expressing one or more B-cell antigens or representing malignant transformations of B-lymphocytes. "However, reports on TET2 mutations in B cell neoplasms are rare, and little is known about DNA hydroxymethylation in CLL." (PMID 27980696, 2016).
blast phase (1 paper, 2020). "Importantly, mutations in IDH1/2 or TET2 are not equally distributed across disease entities in that IDH1/2 are more frequent in blast phase disease whereas TET2 occurs with equal frequency in chronic and blast phase disease." (PMID 32781570, 2020).
blood disease (1 paper, 2022). A disease that occurs in the blood. "Therefore, the JAK2/TET2/HOXA9 motif shares all the required properties for observing a clinical divergence in blood diseases." (PMID 36192425, 2022).
bone cancer (1 paper, 2023). A primary or metastatic malignant neoplasm affecting the bone or articular cartilage. "According to qPCR results, TET1 and TRPV4 mRNA levels gradually increased after the onset of bone cancer pain compared to those in the sham group, but TET2 mRNA levels remained constant over time." (PMID 37190609, 2023). "This suggested that TET1 was specifically highly expressed in bone cancer pain compared to TET2." (PMID 37190609, 2023).
brain cancer (1 paper, 2013). A primary or metastatic malignant neoplasm affecting the brain. "Overall TET2 and IDH1/2 mutations are being mainly described in haematopoietic and brain cancers, but recently, it was shown that 5-hydroxymethylcytosine depletion was detected in those and other cancers such as squamous cell lung cancer, in the absence of TET2 and IDH mutations." (PMID 23998913, 2013).
brainstem tumour (1 paper, 2023). "In this study, we developed a Drosophila model to understand the impact of expression of wild type mammalian TET2 as well as a mutation Arginine 43 to Glycine (R43G) that was identified in DIPG, a brainstem tumour that is highly aggressive and difficult to treat surgically." (PMID 36989121, 2023).
Burkitt lymphoma (1 paper, 2019). A rare form of malignant mature B-cell non-Hodgkin lymphoma. "We conclude that high TET1 and low TET2 expression levels in mouse T-ALL and human Burkitt lymphoma-like cells are directly MYC-dependent and are inversed upon MYC inactivation." (PMID 31266538, 2019). "Together, these results indicate that TET1 expression is high, while TET2 is low in T-ALL derived from EμSRα-tTAα;tet-o-MYC and in human Burkitt lymphoma, revealing a direct correlation between MYC and TET1, and an inverse correlation between MYC and TET2 expression levels." (PMID 31266538, 2019).
cardiac ischemia (1 paper, 2021). "Mutation of the Tet2 (Tet methylcytosine dioxygenase 2) gene in hematopoietic stem cells or myeloid cells aggravated cardiac remodeling and function following pressure overload or cardiac ischemia; these effects were inhibited by a selective NLRP3 inflammasome inhibitor MCC950." (PMID 34776995, 2021).
cardiotoxicity (1 paper, 2023). Toxicity that impairs or damages the heart. "In a larger biopsy cohort, it was shown that Tet2 was more abundantly expressed in cardiotoxicity biopsies vs. control biopsies and vs. non-ischemic cardiomyopathy patients." (PMID 36970338, 2023). "Moreover, in a larger biopsy cohort, it was shown that Tet2 expression was more abundantly expressed in cardiotoxicity biopsies vs. control biopsies, but also compared with non-cardiotoxic non-ischemic cardiomyopathy patients." (PMID 36970338, 2023).
cephalocele (1 paper, 2016). A congenital neural tube closure defect resulting in the protrusion of the brain through a skull opening. "The presence of a lipomatous cephalocele in Tet1/Tet2 double knockouts was not reported." (PMID 26989192, 2016).
Chronic colitis (1 paper, 2025). A chronic inflammatory disease of the large intestine (colon, cecum and rectum). "Recently, several pieces of experimental studies including ours demonstrated that intervention of IL-1 signaling mitigates the Tet2 mutation–induced aberrant hematopoiesis and associated chronic inflammation (i.e., chronic colitis) (40Preprint, 52, 53)." (PMID 39537342, 2025).
congenital neutropenia (1 paper, 2020). "show that acquisition of a mutation in Cxxc4 results in increased CXXC4 protein levels, reduced TET2 protein, increased inflammatory signaling, and leukemic progression of a CSF3R/RUNX1 mutant mouse model of severe congenital neutropenia (SCN)." (PMID 33205068, 2020).
conjunctival melanomas (1 paper, 2021). "A significant 5-hmC and TET2 loss was identified in conjunctival melanoma comparing to nevus, as well as a significant correlation between TET2 and 5-hmC expression." (PMID 34198758, 2021). "It is possible to speculate that this 5-mC increase in conjunctival melanomas might possibly be linked to decreased TET2 levels identified in our study." (PMID 34198758, 2021). "In our study, we focused on the level of TET2 detected by the RNA ISH technique: our results showed a significant decrease in TET2 in conjunctival melanomas compared to nevi." (PMID 34198758, 2021). "Methods: 5-methylcytosine (5-mC), 5-hmC and TET2 were respectively identified by immunohistochemistry and RNA ISH in 40 conjunctival nevi and 37 conjunctival melanomas." (PMID 34198758, 2021). "As investigations of epigenetic alterations occurring in conjunctival melanoma have not been thoroughly explored, we assessed in this study the expression of 5-hmC, 5-mC and TET2 in benign and malignant conjunctival melanocytic proliferations." (PMID 34198758, 2021).
corneal diseases (1 paper, 2023). "Our findings point to a potential role of TET2-inducing strategies for the treatment of corneal diseases associated with abnormal epithelial maturation." (PMID 36769164, 2023).